OGG1 (8-oxoguanine DNA glycosylase)
Diseases named in the same sentence as OGG1 in open-access papers (continued):
Sharing a sentence is not in itself a finding about the gene and the disease.
chronic cutaneous lupus erythematosus (1 paper, 2020). Chronic cutaneous lupus erythematosus (CCLE) is a form of cutaneous lupus erythematosus (CLE) that includes five different forms: discoid lupus erythematosus (DLE), chilblain lupus, hypertrophic or verrucous lupus erythematosus, lupus erythematosus tumidus, and lupus erythematosus panniculitis. "In translating these results to human disease, we found decreased OGG1 expression in SLE patients associated with cutaneous involvement, and that lesional skin from patients with chronic cutaneous lupus erythematosus had reduced OGG1 expression compared to non-lesional areas." (PMID 33072095, 2020).
Clostridium perfringens infection (1 paper, 2020). "In the present study, the expression of occludin, ZO-1, GLP2, OGG1 and TFF2 genes increased in the wall of the small intestine, which indicates that C. perfringens infection in turkeys compromised intestinal barrier integrity." (PMID 32264939, 2020). "The expression of occludin, ZO-1, GLP2, OGG1 and TFF2 genes increased in the wall of the ileum (P < 0.001) in response to C. perfringens infection." (PMID 32264939, 2020). "Clostridium perfringens infection increased the expression of occludin, ZO-1, GLP2, OGG1 and TFF2 genes (P < 0.001) in the wall of the ileum." (PMID 32264939, 2020).
cognitive decline (1 paper, 2020). "Our results indicate that loss of HDAC1 results in age-dependent cognitive decline, paralleled by reduced OGG1 activity and 8-oxoG lesion accumulation." (PMID 32424276, 2020).
colitis (1 paper, 2020). Inflammation of the colon. "NLRP6-/- mice exhibit reduced IL-18 levels in intestinal epithelial cells and, interestingly, like Ogg1-/- mice were highly susceptible to DSS-induced colitis." (PMID 31935236, 2020). "In analyzing the marked alterations in the gut microbial profile of Ogg1-/- mice, we were struck by the observation that several of the changes in gut microbes in Ogg1-/- mice have been reported to play a role in intestinal inflammation and colitis." (PMID 31935236, 2020). "Alternatively, it is plausible that upon acute induction of severe DNA damage across the genome, as might occur during acute colitis, channeling and sequestration of OGG1 to its DNA repair functionality may result in its reduced availability as a transcriptional regulator." (PMID 31935236, 2020).
colon adenoma (1 paper, 2014). An adenoma that arises from the colon. "Indeed, several studies have demonstrated that the expression of OGG1 and PARP-1 is enhanced as a result of oxidative stress, and our recently published paper has shown increased oxidative stress in colon adenoma and carcinoma patients." (PMID 25526641, 2014).
dermatitis (1 paper, 2022). An inflammatory process affecting the skin. "On the one hand OGG1 deficient mice have been shown to develop less severe inflammation in contact hypersensitivity (dermatitis) and endotoxin shock." (PMID 36289805, 2022). "OGG1 has been linked to the inflammatory response (e.g., in in contact hypersensitivity (dermatitis), endotoxin shock and allergic lung inflammation." (PMID 36289805, 2022).
dysplasia (1 paper, 2006). A usually neoplastic transformation of the cell, associated with altered architectural tissue patterns. "For both OGG1 and RAI we found that the expression was lower in normal colonic mucosa from CRC patients than in normal colonic mucosa from persons with mild/moderate dysplasia." (PMID 16914027, 2006).
emphysema (1 paper, 2019). "Moreover, OGG1 levels were also reduced in severe compared to mild emphysema." (PMID 30696938, 2019). "Moreover, we did not detect activation of DNA damage repair in ATII cells in emphysema as shown by low levels of OGG1, γH2AX and XLF." (PMID 30696938, 2019).
epilepsy (1 paper, 2023). A brain disorder characterized by episodes of abnormally increased neuronal discharge resulting in transient episodes of sensory or motor neurological dysfunction, or psychic dysfunction. "Present study was purposed to figure out the expression level of mitochondrial sirtuins (SIRT3, SIRT4, SIRT5) and related genes (GDH, OGG1-2α, SOD1, SOD2, HIF1α and PARP1) in 153 glioma tissue samples and 200 brain tissue samples from epilepsy patients (taken as controls)." (PMID 36809279, 2023).
gestational diabetes (1 paper, 2025). Carbohydrate intolerance first diagnosed during pregnancy. "A small study found increased expression of hOGG1 (human 8-oxoguanine DNA glycosylase) mRNA in placentas from pregnancies with pre-eclampsia (n = 20) or gestational diabetes (GDM, n = 20) indicative of oxidative stress, compared with 20 controls." (PMID 39796238, 2025).
glioma (1 paper, 2023). A benign or malignant brain and spinal cord tumor that arises from glial cells (astrocytes, oligodendrocytes, ependymal cells). "The aim of present study was to elucidate the role of expression deregulations of mitochondrial sirtuin genes and co-expression with their associated proteins (SOD1, SOD2, OGG1-2α, PARP1, GDH and HIF1α) in glioma." (PMID 36809279, 2023). "Results analysis showed significant down-regulation of SIRT4 (p = 0.0337), SIRT5 (p<0.0001), GDH (p = 0.0305), OGG1-2α (p = 0.0001), SOD1 (p<0.0001) and SOD2 (p<0.0001) in glioma patients compared to controls." (PMID 36809279, 2023).
glomerulonephritis (1 paper, 2020). A renal disorder characterized by damage in the glomeruli. "We therefore investigated the role of OGG1 in the pristane-induced lupus (PIL) mouse model of IFN-driven SLE, which recapitulates numerous human SLE manifestations, including elevated type I IFNs, autoantibody generation, arthritis, and severe glomerulonephritis." (PMID 33072095, 2020).
hemangiosarcomas (1 paper, 2017). "Interestingly, hemangiosarcomas were detected only in the DMBDD-treated Ogg1−/− mice." (PMID 28820464, 2017).
hemorrhagic cystitis (1 paper, 2016). Inflammation of the bladder resulting in bloody urine. "Ogg1 deficiency exhibited tissue-specific increases in both signal I and signal II pyroptotic cascades, associated with the mice in recruiting inflammatory infiltrates and developing hemorrhagic cystitis downstream of IL-1ß expression." (PMID 27995963, 2016). "The aim of this study was to examine how the bladder Ogg1 gene is regulated in cell culture and animal models of hemorrhagic cystitis." (PMID 27995963, 2016). "However, the inversely proportional expression of Ogg1 and the pathologic manifestations of hemorrhagic cystitis described here are supportive of clinical testing." (PMID 27995963, 2016).
HIVinfection (1 paper, 2011). "Cells with acomplete deletion of OGG1 and MUTYH had less HIV infection than eitherheteroallelic deletion of OGG1 or MUTYH, indicating that these BER genes playnon-redundant roles in the HIV life cycle." (PMID 21448273, 2011). "Similar to the siRNAexperiments, deletion of MUTYH, OGG1, and POLB led to decreased HIV infection." (PMID 21448273, 2011).
hyperreactivity (1 paper, 2025). "Another study has previously shown that inhibition of a DNA repair enzyme, i.e. 8-oxoguanine DNA glycosylase-1 (OGG1) reduces inflammation and bronchial hyperreactivity in a murine model through interference with the transcriptional activity of NF-kB." (PMID 40087604, 2025).
hypertrophy (1 paper, 2022). Hypertrophy is the increase in the volume of an organ or tissue due to the enlargement of its component cells. "In addition, cardiac overexpression of human mitochondrial isoform of OGG1 (OGG1-2a) led to a reduction in mtDNA damage and cardiac fibrosis in a mouse pressure overload model of cardiac hypertrophy." (PMID 35391931, 2022).
hypothyroidism (1 paper, 2024). Abnormally low levels of thyroid hormone. "In particular, the decrease in OGG1 and POLγ proteins suggests a possible impairment in the maintenance of mitochondrial DNA integrity in hypothyroidism." (PMID 39301315, 2024).
invasive ductal carcinoma (1 paper, 2015). "Frequency of OGG1 mutations was observed to be significantly higher in patients with invasive ductal carcinoma (p < 0.0001), negative ER (p < 0.001), and negative PR status (p < 0.01)." (PMID 26089588, 2015).
liver cancer (1 paper, 2017). An epithelial or non-epithelial malignant neoplasm that arises from the liver. "Furthermore, it was suggested that a positive correlation exists among human liver cancer stage, 8-OHdG levels, Ogg1 polymorphisms, ALT/GGT levels, telomerase activity, and overexpression of miR-92, a microRNA that plays a role in both the apoptotic process and the cellular proliferation pathways." (PMID 28785378, 2017). "Coordinated overexpression of Ogg1 and Nrf2 and downregulation in Keap1 expression were previously shown in HepG2 human liver cancer cell line after the menadione and H2O2/Fe2+ exposure." (PMID 28785378, 2017).
lung tumors (1 paper, 2015). "Comparable to our results, deficiencies of two DNA repair genes (Myh−/− and Ogg1−/−) predisposed mice to lung tumors, and this was attributed largely to acquired K-rasG12D mutations." (PMID 25773971, 2015).
mood disorder (1 paper, 2021). A cognitive disorder a disturbance in which the person's mood is hypothesized to be the main underlying feature. "Patients with mood disorders had increased 8-oxo-dG and decreased gene expression levels of OGG1 during depressive episodes and these changes might be reversed by the resolution of depressive symptoms." (PMID 34200513, 2021).
neuropathy (1 paper, 2022). A disorder affecting the nervous system that manifests with pain, tingling, numbness, and/or muscle weakness. "Our studies demonstrate that inhibition of OGG1 and APE1 endonuclease activity enhances oxidative DNA damage and exacerbates neurotoxicity, thus limiting oxidative DNA damage in sensory neurons that might alleviate cisplatin-induced neuropathy." (PMID 35163831, 2022).
osteosarcoma (1 paper, 2023). A usually aggressive malignant bone-forming mesenchymal neoplasm, predominantly affecting adolescents and young adults. "In this study, a total of four transcriptional osteosarcoma-related DNA sequences were screened out, which were mTOR, OGG1, EGFR, and PDGFR-β." (PMID 37065446, 2023).
polycystic ovary syndrome (1 paper, 2025). A disorder that manifests as multiple cysts on the ovaries. "This evidence further supports the anti-apoptotic and pro-inflammatory roles of OGG1 in the pathogenesis of polycystic ovary syndrome." (PMID 40813502, 2025). "However, the precise role of OGG1 in Polycystic ovary syndrome remains to be fully elucidated." (PMID 40813502, 2025).
polyposis (1 paper, 2020). "OGG1 was not part of our gene panel, and its role in hereditary CRC/polyposis is controversial." (PMID 33193653, 2020).
prion disease (1 paper, 2016). A transmissible disease that is caused by a protein that is able to induce abnormal folding of normal cellular proteins, leading to characteristic spongiform brain changes, which are associated with neuronal loss without an inflammatory response. "There was a significant decrease in expression at either onset or end-stage or both for some of the DNA glycosylases (Neil1, Neil2 and Ogg1) in wild-type mice, demonstrating a lack of compensatory up-regulation of brain DNA glycosylases in prion disease." (PMID 27886261, 2016).
pulmonary disease (1 paper, 2022). "In summary, studies performed so far have given enough evidence that OGG1 plays important role in pulmonary diseases and show the necessity of further investigation on its relative mechanism." (PMID 35624797, 2022). "This review intends to make an overall summary of the mechanism through which OGG1 regulates gene expression and the role of OGG1 in pulmonary diseases." (PMID 35624797, 2022). "This review collected and sorted evidence over the biological function of OGG1 and its new role as a regulator, trying to dig deep into the connection between OGG1 and pulmonary disease and figuring out its potential possibility to work as target therapy in the future." (PMID 35624797, 2022).
renal adenoma (1 paper, 2017). An adenoma arising from the renal cortex. "Only one Ogg1+/+ DMBDD-treated mouse developed renal adenoma." (PMID 28820464, 2017).
renal carcinoma (1 paper, 2018). A carcinoma arising from the epithelium of the renal parenchyma or the renal pelvis. "Our previous data show that activation of AMPK by AICAR results in decreased p70S6K phosphorylation and increased DNA repair expression protein OGG1 expression and rapamycin activates AMPK leading to increased OGG1 protein expression in renal cancer cells." (PMID 30250638, 2018).
renal cell carcinoma (1 paper, 2008). "In addition, the predominant expression of OGG1 in the cortex and its decreased expression and activity in the Eker rat may account for the predominant cortical localization of renal cell carcinoma." (PMID 18218111, 2008).
sarcoma (1 paper, 2017). A usually aggressive malignant neoplasm of the soft tissue or bone. "In addition, uterine tumors (endometrial adenomas and sarcomas) were obvious only in PB-applied Ogg1−/− and Ogg1+/+, but not in untreated Ogg1−/− and Ogg1+/+ female mice." (PMID 28785378, 2017).
status epilepticus (1 paper, 2012). Status epilepticus is defined as a continuous seizure lasting more than 30 min, or two or more seizures without full recovery of consciousness between any of them. "Mitochondrial OGG1 was down-regulated both at mRNA and protein levels in a pilocarpine-induced status epilepticus in the hippocampi of male rats, suggesting that lowering of mitochondrial BER enzymes may aggravate mtDNA damage and mitochondrial deficiency after the onset of a status epilepticus." (PMID 23203191, 2012).
T-cell lymphoblastic acute leukemia (1 paper, 2021). "The OGG1 glycosylase function depletion has been seen to obstruct pathological conditions such as inflammation, A3 T-cell lymphoblastic acute leukemia growth, and neurodegenerative diseases, thus warranting OGG1 as an attractive anti-cancer enzyme." (PMID 34948899, 2021).
thyroid tumor (1 paper, 2025). A benign or malignant neoplasm affecting the thyroid gland. "While Ogg1 mRNA expression was not modified, we observed a downregulation of Gpx2 and Nqo1 mRNA expression in thyroid tumors from 2- and 8-month-old RET/PTC3 Dicer1(+/+) mice compared to WT thyroids, suggesting that redox homeostasis is unbalanced in RET/PTC3 tumors." (PMID 41002430, 2025).
urinary tract infection (1 paper, 2017). "One non-treated control Ogg1+/+ male mouse was found moribund at Week 27 due to a urinary tract infection." (PMID 28820464, 2017).
cancer (152 papers, 2002 to 2026). A tumor composed of atypical neoplastic, often pleomorphic cells that invade other tissues. "Somatic mutations in the OGG1 gene are frequently observed in various human cancers, and the gene exhibits a high degree of polymorphism in the general population." (PMID 40813502, 2025). "Here, the authors employ structure-based docking screens of vast fragment libraries to identify inhibitors of 8-oxoguanine DNA glycosylase, a difficult drug target implicated in cancer and inflammation." (PMID 39966348, 2025). "Wild-type OGG1 and, to an even greater extent, its cancer-associated variant OGG1 S326C are inactivated through oxidation of critical Cys residues by physiological inflammation-induced levels of ROS and by the free radical cellular messenger, NO." (PMID 41465236, 2025). "Mutations like Ser326Cys can reduce OGG1’s repair efficiency, leading to genomic instability and an increased risk of cancer." (PMID 39851540, 2025). "To determine the functional consequences of SIRT2-mediated regulation of OGG1 transcription, we identified 37 cancer-associated mutations in SIRT2 through data mining using the TCGA database." (PMID 38554113, 2024). "Accordingly, human cells or cancer genomes with bi-allelic OGG1 or MUTYH mutations display respective SBS188,18,23 and SBS3624 mutation signatures, both of which are dominated by C to A substitutions." (PMID 39715760, 2024). "Taken together, our data demonstrate that at least five cancer-derived SIRT2 mutations reduce the capability of SIRT2 to promote OGG1 transcription to enhance BER efficiency, thereby contributing to tumorigenesis." (PMID 38554113, 2024). "Variants and loss of multiple of the factors in this study lead to cancer and neurodegenerative disease including OGG1 and Pol η." (PMID 39715760, 2024). "The data showed that OGG1‐deficiency‐suppressed cancer cell migration, invasion and proliferation were rescued by SYT7 overexpression." (PMID 39235072, 2024). "Another study highlighted that the oxidized form of the OGG1-S326C polymorphic variant, which has a cysteine substitution at position 326, is associated with an increased risk of cancer, as observed in several molecular epidemiological studies." (PMID 39744126, 2024). "We also identified several cancer-associated SIRT2 mutants with loss of the stimulatory effects on OGG1 transcription and BER efficiency, indicating that SIRT2 functions as a tumor suppressor by promoting BER for genome stabilization." (PMID 38554113, 2024). "Although cancer is a highly heterogeneous disease, at least two powerful examples demonstrate that OGG1 S326C can be implicated in malignant progression." (PMID 38201575, 2023). "Considering all these findings, we decided to evaluate the potential therapeutic impact of OGG1 inhibition on BRCA1-deficient cancer cells as well as its interaction with PARP inhibition." (PMID 35619904, 2022). "Many studies have explored the link between OGG1 Ser326Cys polymorphism and cancer susceptibility; however, the results are controversial." (PMID 36497058, 2022). "Strong cancer susceptibility was observed in OGG1 and Mutyh double-knockdown mice, in which 8-oxoG accumulated in the liver, lung, and small intestine but not in the brain, kidney, and spleen, showing organ specificity." (PMID 36620083, 2022). "The OGG1 gene has somatic mutations in some human cancer cells, which are highly polymorphic in the human population." (PMID 36620083, 2022). "Both X-ray repair cross-complementing group 1 (XRCC1) and 8-oxoguanine DNA glycosylase 1 (OGG1) are components of the BER pathway, and polymorphisms in XRCC1 and OGG1 are clinically important in various human cancers." (PMID 36497451, 2022). "We found carriers of the OGG1 Cys326 allele are at risk of a significantly worse outcome, in particular concerning cancer-specific survival." (PMID 34199885, 2021). "The Ser326Cys polymorphism in the human OGG1 gene affected clinical outcome, in particular cancer-specific survival (CSS)." (PMID 34199885, 2021).